CXCR4 (C-X-C motif chemokine receptor 4)
Diseases named in the same sentence as CXCR4 in open-access papers (continued):
Sharing a sentence is not in itself a finding about the gene and the disease.
tumor (continued). "For instance, CXCR4 is highly expressed on many types of tumor cells allowing them to hijack CXCL12-CXCR4 pathway for metastasis of tumor cells to distinct organ sites where CXCL12 is highly expressed." (PMID 33096938, 2020). "KRas G12V showed higher tumor cell survival, invasion, and CXCR4 expressing intravasated tumor emboli than KRas G13D." (PMID 32486141, 2020). "The CXCL12-CXCR4 signaling axis plays an important role in tumor progression and metastasis, but also in treatment-induced recruitment of CXCR4-expressing cytotoxic immune cells." (PMID 31802362, 2020). "For example, stromal cells in secondary lymphatic tissues constitutively secrete chemokines, such as CXCL12, that facilitate homing and survival of tumor cells expressing its main receptor, CXCR4." (PMID 32370190, 2020). "CXCL12 is a chemokine ubiquitously expressed in many tissues and cell types, and the interaction of CXCL12 and its receptor, CXCR4, is involved in multiple processes in the tumor microenvironment." (PMID 33261029, 2020). "CXCL12 (SDF-1), ligand of CXCR4, is expressed at the sites of tumor metastasis and is involved in homing of the tumors to different organs." (PMID 32630806, 2020). "It has been reported that CXCL12/CXCR4 axis plays an important role in tumor angiogenesis, and protein and mRNA levels of CXCL12 are associated with human BCa progression." (PMID 32675942, 2020). "CXCL12/CXCR4 axis synergizes with CD38 to support migration as a central step in tumor disease progression." (PMID 33123122, 2020). "Conclusion, our clinical and experimental evidence strongly support that miR-204-5p act as a tumor suppressor in GC by targeting CXCR4 and CXCL12, thus regulating invasion and migration." (PMID 32231725, 2020). "CXCR4 is a chemokine receptor, which regulates tumor growth, proliferation, and metastasis in cancers." (PMID 32306562, 2020). "Inhibition of CXCR4 exaggerates the anti-tumor immune response and CXCR4-targeted therapy is a possible therapeutic option to eradicate CSCs." (PMID 32972006, 2020). "CXCL12 are small pro-inflammatory chemo-attractant cytokines that bind to a specific receptor CXCR4 with a role in angiogenesis, tumor progression, metastasis, and cell survival." (PMID 33092204, 2020). "More specifically, the relative CXCR4+ tumor accumulation significantly decreased from around 60–75% to 15–20% in labeled nanoparticles while their off-target tissue uptake dramatically increased in both models." (PMID 33105866, 2020). "Although the highest %ID/g in the tumor was acquired at 6 h after the administration of 211At-CXCR4 mAb, it was still lower than those in the lung, heart, and kidneys." (PMID 32321944, 2020). "CXCR4 desensitization in tumor cells is a potential therapy in TNBC and other overexpressed CXCR4 tumor cells." (PMID 33195200, 2020). "T22-GFP-H6 nanoparticles show high architectonic stability in vivo and selectively internalize into CXCR4+ cells in the primary tumor and in macro and micro-metastasis in a disseminated cancer model." (PMID 33105866, 2020). "CXCL12/CXCR4 signal pathway participates in tumor progression and metastasis and survival, except for angiogenesis." (PMID 33292246, 2020). "mTOR signaling and CXCL12/CXCR4 axis have been reared as a positive feedback loop to influence the tumor migration and CXCL12 secretion." (PMID 32483450, 2020). "CXCL12, significantly upregulated in the tumor microenvironment, increases adhesion, migration, and homing of CXCR4-positive progenitor cells to ischemic tissues requiring regeneration and neovascularisation." (PMID 33260925, 2020). "CXCR4 is highly expressed on aggressive/malignant tumor cells and plays a critical role in the homing of cancer cells to distant sites following binding to its ligand CXCL12." (PMID 32239371, 2020).
tumor (continued). "In contrast, in bladder, lung squamous, pancreatic, prostate and rectum carcinomas, CXCR4 showed significantly higher mRNA expression levels in normal cells adjacent to tumor tissue compared to cancer cells." (PMID 32260318, 2020). "CXCR4-positive tumor cells migrate along the CXCL12 gradient to distant organs, such as the CXCL12-rich BM microenvironment." (PMID 32260318, 2020). "To further explain the organotropic dissemination of DLBCL, we analyzed the expression of chemokine receptors in the tumor microenvironment, which promote the migration of malignant B cells, and discovered a relationship between CXCR4 and bone marrow invasion." (PMID 33252851, 2020). "Activation of the CXCR4/CXCL12 pathway is considered to be a major contributor to tumor invasion of surrounding tissues." (PMID 32239371, 2020). "The CXCR2 ligands (CXCL1, -2 and -5) recruit CXCR2+ neutrophils into the tumor microenvironment, which interact with cancer cells and induce expression of metastasis-involved genes such as CXCR4 and MMP-2." (PMID 33096815, 2020). "Along the same lines, anti-PD-L1 synergized with the CXCR4-inhibiting drug plerixafor in killing tumor cells in a mouse pancreatic model." (PMID 32582148, 2020). "In tumors, CXCR4/CXCR7/CXCL12 pathway is involved in the complex scenario of tumor progression, including invasion, chemotaxis, and angiogenesis." (PMID 33260925, 2020). "CXCR4-mediated cell surface MHC-I downregulation in cancer progression facilitated tumor evasion of immune surveillance." (PMID 32308549, 2020). "The tumor-to-muscle ratio of 211At-CXCR4 mAb uptake was highest (8.51 ±6.14) at 6 h, at this time point, the tumor-to-muscle ratio of 125I-CXCR4 mAb uptake was 5.51 ± 0.74." (PMID 32321944, 2020). "Lymphatic vessels can attract CXCR4-expressing tumor cells to promote lymphatic metastasis, and CXCR4 expression is also associated with lymphatic metastasis." (PMID 32244922, 2020). "Along with its ligand CXCL12, CXCR4 controls the transduction of different downstream signaling pathways that are profoundly involved in tumor cell survival, proliferation, and migration." (PMID 33363463, 2020). "CXCL12 and its receptor, CXCR4, play pivotal roles in tumor development, progression, angiogenesis, and metastasis in various types of cancers." (PMID 32824865, 2020). "Intriguingly, CXCL12/CXCR4 interaction induced mTOR signaling not only influences the immune cells chemotaxis, but also participates in tumor cells migration, such as gastric, pancreatic and renal cancer cells 161-163." (PMID 32483450, 2020). "The CXCL12/CXCR4 axis is also involved in enhancing angiogenesis in the tumor environment, and therefore, metastasis." (PMID 32585812, 2020). "In cancer stem cells, CXCR4 is upregulated and plays an irreplaceable role in perivascular invasion, a specific tumor behavior in GBM." (PMID 33329750, 2020). "High CXCR4 expression promoted tumor invasiveness, enhanced chemoresistance and inhibited apoptosis of lung ASC in vitro." (PMID 31949484, 2020). "Inhibiting this effect by usage of a neutralizing antibody against CXCR4 diminished tumor size and intratumor blood vessel formation." (PMID 32585812, 2020). "Previous work had focused on the role of CXCL12 and its receptor CXCR4 in tumor development and how they affected overall prognosis of cancer patients." (PMID 33129326, 2020). "The authors revealed that the overexpression of CXCR4 significantly correlated with a more advanced tumor stage and PC progression." (PMID 32867211, 2020). "In GC, CXCR4 can regulate the tumor epithelial‐to‐mesenchymal transition (EMT) and the progression through the PI3K/AKT pathway, or induce EMT through the cross talk with c‐MET signaling." (PMID 32306562, 2020). "Cxcr4 has been reported to be involved in many important processes surrounding tumor formation and metastasis, including cell survival, proliferation, adhesion, migration, and invasion." (PMID 32978388, 2020).
tumor (continued). "CA-4-NPs can accumulate around tumor blood vessels and shut down tumor microvasculature but it also significantly enhanced CXCR4 expression." (PMID 32486408, 2020). "Similar failure in phagocytosis was observed in microglia suggesting that the activation of CXCL12/CXCR4 can induce tumor-supporting functions in macrophages and microglia already at an early stage of tumor development." (PMID 33096815, 2020). "Plerixafor (AMD3100), a CXCR4 antagonist, inhibits the BM-mediated tumor vasculature in ES by reducing PDGFRβ expression through the disruption of the SDF-1α/CXCR4 axis." (PMID 32754598, 2020). "Studies with a neuroblastoma or prostate tumor mouse model showed that high CXCL12 expression in the tumor cells recruited CXCR4-positive monocytes and stimulated the formation of new tumor blood vessels." (PMID 33392074, 2020). "CXCR4/CXCL12 axis inhibition has been demonstrated to revert tolerogenic polarization of tumor microenvironment and to restore sensitivity to CTLA-4 and PD-1 ICIs, overall representing a novel and effective way to counteract ICIs resistance." (PMID 33123122, 2020). "This review focuses on recent reports pointing to its pivotal role in tissue regeneration and stem cell activation, and discusses the connection to the known role of CXCR4 in promoting tumor growth." (PMID 32983169, 2020). "Spatial and temporal changes in the distribution of 211At-CXCR4 mAb in the tumor should be accurately measured for accurate dosimetry." (PMID 32321944, 2020). "CD105 and CXCR4 alone, used in previous studies to identify CSCs in kidney cancers, were less predictive of tumor progression." (PMID 32066735, 2020). "The CXCL12/CXCR4 pair promotes tumor cell growth and the proliferation of glioblastoma cells via the ERK1/2 and AKT pathways." (PMID 31991604, 2020). "miR-494 targets CXCR4 through the Wnt/β-catenin signaling pathway, thereby inhibiting Breast Neoplasms progression in vitro." (PMID 33193744, 2020). "CXCR4 has been reported to be overexpressed in a variety of tumor cells and is involved in tumor proliferation, invasion, metastasis, and worse prognosis." (PMID 32874785, 2020). "CXCL12 is involved in induction tumour growth, migration and invasiveness via engagement of C-X-C chemokine receptor type 4 (CXCR4) on malignant cells and also promotes tumour angiogenesis through mediation of endothelial progenitor molecules." (PMID 32466214, 2020). "Experimental evidence revealed that secretion of osteoblastic CXCL12 triggers dissemination of tumor cells from the bloodstream to the target site by binding the receptor C-X-C chemokine receptor type 4 (CXCR4) located on the tumor cells." (PMID 33747899, 2020). "Accumulating evidence suggests that the CXCL12/CXCR4/CXCR7 axis plays a pivotal role in tumor development, survival, angiogenesis, metastasis, and tumor microenvironment." (PMID 33363463, 2020). "Many previous studies have demonstrated the importance of the SDF-1/CXCR4 axis in tumor dissemination and cancer progression." (PMID 32836215, 2020). "Increased secretion of CXCL12 by the tumor, for example, as a result of hypoxia or treatment, stimulates the infiltration of CXCR4 expressing immune cells." (PMID 31802362, 2020). "For example, the cytokine CXCL-12 is secreted by CAFs, while its receptor CXCR-4 is found mainly on tumor cells." (PMID 33585565, 2020). "CXCR4 activation induces tumor angiogenesis, inflammation, and cellular reprogramming, contributing to metastasis." (PMID 32260318, 2020). "CXCR4 is one of the most well-studied chemokine systems in tumor growth, metastasis, and angiogenesis." (PMID 32635336, 2020). "The tumor showed gradually increased uptake of 211At-CXCR4 mAb, and the highest uptake was obtained at 6 h." (PMID 32321944, 2020). "Accordingly, CXCR4-expressing macrophages are called “transporters”, which carry tumor cells toward the blood vessel and present them to perivascular macrophages." (PMID 32943996, 2020).
tumor (continued). "CXCR4 was found to be correlated with PCa prognosis, and PCa patients with elevated expression of CXCR4 in tumor tissues have a higher survival rate than those with relatively low expression of CXCR4." (PMID 33194726, 2020). "CXCL12/CXCR4 is a well-investigated axis that is strongly involved in all stages of tumor progression in many kinds of cancer." (PMID 31991604, 2020). "The use of biodegradable polymeric nanoparticles to overexpress CXCR-4 in human adipose MSCs enhanced cell migration velocity and increased their co-localization within the hypoxic area of the tumor." (PMID 32046010, 2020). "Overall, CXCR4 protein expression correlated with qPCR findings with increased CXCR4 protein in tumor colonocytes compared to colonocytes from adjacent mucosa." (PMID 32110952, 2020). "For example, a CXCR4 neutralizing antibody and shRNA knockdown of the CXCR4 receptor significantly reduced tumor cell invasion." (PMID 33363463, 2020). "The preceding sections have highlighted that CXCR4 activation can drive both cell migration and cell proliferation, at least in vascular, progenitor and tumor cells." (PMID 32983169, 2020). "In D-17 we highlighted the basal expression of both CD44 and CXCR4; the first is a trans-membrane protein involved in the tumor microenvironment that interacts with various components of the extracellular matrix, cytokines and growth factors." (PMID 33126659, 2020). "Autocrine activation of PDGFRα induced tumorigenesis and metastasis in advanced skin squamous cell carcinomas (SCCs) via upregulation and secretion of SDF-1α, and then SDF-1/CXCR4 induced PDGFR-induced tumor cell invasion and metastasis." (PMID 32754598, 2020). "To enhance the migration capability of CAR NK cells toward tumor cells residing in the bone marrow, we generated huCAR19.CXCR4-LV particles delivering CXCR4 in addition to the CAR construct." (PMID 32983147, 2020). "The inhibition of CXCR4, the CXCL12 receptor, using the clinical approved CXCR4 antagonist plerixafor, reduced EMT-associated PASC motility in vitro, and xenograft tumor growth in vivo." (PMID 32153500, 2020). "In our present study, we reported that double-targeted knockdown of miR-21 and CXCR4 presented a better suppressive effect on tumor progression when compared to single-targeted knockdown of miR-21 or CXCR4 alone." (PMID 33123586, 2020). "In the current study, we analyzed the newly identified direct phosphorylation-dependent binding of LASP1 to AKT1 and CXCR4, two major players in tumor progression." (PMID 32075106, 2020). "These processes occur by direct binding of given chemokine to a respective chemokine receptor, CCR2 and CXCR4, which are expressed by tumor vessels, or by promoting the recruitment of leukocytes." (PMID 32456359, 2020). "Inhibition of CXCL12/CXCR4 axis using a CXCR4 antagonist compromised tumor growth by altering the interaction of cancer cells with osteoblast niches." (PMID 33747899, 2020). "Deletion of Cxcl12 in endothelial cells or pharmacological blockage of Cxcr4 is known to inhibit antral tumor growth." (PMID 31963721, 2020). "These promising results from in vitro studies supported proceeding to in vivo PET imaging of CXCR4 expression in tumor-bearing animal models, using the newly developed radiolabeled cyclam derivatives." (PMID 32239371, 2020). "Due to the central role in tumour development, a variety of inhibitors of the CXCR4/CXCL12 interaction has been developed during the last decade." (PMID 32019275, 2020). "In contrast, CXCR4, which has been shown to be inversely related to the expression of perforin and its blockage was shown to activate the migration and tumor-killing ability of CD8+ T cells was found upregulated in advanced HCC." (PMID 33298893, 2020). "Tumor-associated macrophages CD206+ TAMs, which infiltrated at the invasive front, were correlated with CXCR4 expression and liver metastasis." (PMID 32708431, 2020).
tumor (continued). "In a similar fashion to CXCR4 overexpression, tumor homing can be amplified by engineering MSCs to overexpress specific tumor-binding receptors." (PMID 32133358, 2020). "We identified 76Br-HZ270-1 as the best of the 6 radioligands for imaging CXCR4 expression in the s.c. tumor models." (PMID 32239371, 2020). "We suggest that CXCR4 inhibition can facilitate the mobilization of GSCs out of their protective niches as well as the mobilization of macrophages out of the tumor, resulting in a better response to radiotherapy and temozolomide chemotherapy." (PMID 32079173, 2020). "Fluorine-18 labeled pentixafor analog has recently shown high CXCR4 affinity and favorable tumor-to-normal organ ratios in a murine model of human lymphoma." (PMID 32972006, 2020). "In contrast to tumor-infiltrating APCs, pathways related to the positive regulation of immune and defense response, including IL-8/IL-6/IL-3/CXCR4 signaling, TREM1 signaling and leukocyte extravasation pathways were downregulated in I-MDSCs." (PMID 33312958, 2020). "Elevated CXCL12 as well as increased tumor metastasis were detected in skeletal tissues, whereas subsequent treatment with CXCR4 antibody decreased tumor spread." (PMID 32585812, 2020). "The CXCR12/CXCR4 axis has influence on intratumor immune cell subsets and anti-tumor immune response." (PMID 32972006, 2020). "We have demonstrated that CXCL12 is a key player in the migration of CXCR4 positive adult GSCs from the tumor mass toward the SVZ." (PMID 33575218, 2020). "The expression level of CXCR4 was found to be similar between PCa tumor and normal tissues; however, GPR183 was down-regulated in the PCa tumor tissues as compared with the normal tissues." (PMID 33194726, 2020). "Although ELR− CXC chemokines belong to the antiangiogenic CXC chemokine family, ELR− CXC chemokines, including CXCR3, CXCR4, CXCR5, CXCR6, and CXCR7, are associated with tumor growth, proliferation, and metastasis in PC." (PMID 33195424, 2020). "CXCR4 was frequently expressed on breast cancer cells and guided tumor cell spread to the bone, lung, and regional lymph nodes expressing high levels of its ligand CXCL12." (PMID 32943996, 2020). "VHL codifies for a tumor suppressor protein involved in the degradation of hypoxia-inducible factor alpha (HIF1α) and the stromal-derived factor-1 receptor (CXCR4) proteins, which leads to the block of angiogenesis and tumor cell migration." (PMID 31903105, 2020). "CAFs together with endothelial cells generate local CXCL12 gradients to attract CXCR4+ progenitor cells such as endothelial progenitor cells, enhancing tumor angiogenesis." (PMID 33096815, 2020). "To verify the relationship between CXCR4 expression and the clinicopathological features of lung ASC patients, we investigated the expression of CXCR4 in tumor tissues." (PMID 31949484, 2020). "Cancer secreted PTHrP and CXCR4 and the activation of NF-κB as well as tumor-induced osteoclastogenesis within bone tissue were suppressed in the pathological samples after BSA-Au clusters treatments." (PMID 32226538, 2020). "Inhibition of CXCR4 suppresses Treg infiltration into the tumor and increases the anti-tumor immune response." (PMID 32972006, 2020). "Inhibition of circ_0056618 suppressed tumor cell proliferation and metastasis by preventing sponging of miR-206 and the subsequent targeting of CXCR4." (PMID 32943996, 2020). "Migration of cancer cells is directly dependent on the interactions between cell surface molecules on the tumor cells, like CXCR4, and the release of chemokines, like CXCL12, by tissues that are targets for metastases." (PMID 31802362, 2020). "A recent study showed that SDF-1α binds to CXCR7 10-fold more than it does to CXCR4, and is involved in cell survival, adhesion, and tumor development." (PMID 31792315, 2019).